EGFR (epidermal growth factor receptor)
Diseases named in the same sentence as EGFR in open-access papers (continued):
Sharing a sentence is not in itself a finding about the gene and the disease.
pancreatic cancer (continued). "EGFR (also known as ErbB1/HER1) is commonly upregulated in several cancer types including pancreatic cancer, and thus EGFR-targeted therapies have been developed, including monoclonal antibodies against the extracellular domain of EGFR and tyrosine kinase inhibitors (TKIs)." (PMID 33917882, 2021). "Some studies have shown that EGFR is highly expressed in pancreatic cancer." (PMID 34680585, 2021). "Additionally, studies have demonstrated the use of statins in combination with anti-EGFR agents in pancreatic cancer treatment." (PMID 34195085, 2021). "To further investigate the significance of the pYs‐related signaling pathways in human pancreatic cancers, we measured the phosphorylation levels of total Tyrosine, EGFR, and STAT3 in PDAC and adjacent tissues in patients who have received surgical resection of their tumors." (PMID 33783993, 2021). "Interestingly, exosomes from gastric, breast and pancreatic cancer carry members from the human epidermal growth factor receptor (HER) family." (PMID 33803776, 2021). "Indeed, we demonstrated that the EGFR activation that mediated pancreatic cancer tumorigenesis was partly HSF1-dependent in vitro." (PMID 33422093, 2021). "In conclusion, EGFR was important for pancreatic cancer initiation and progression." (PMID 33422093, 2021). "In this context, a recent research work describes the important role of oncogenic K-ras, growth factor receptors (FGFR1 and EGFR) and ROS in regulating PD-L1 expression in pancreatic cancer cells and aids significant new mechanistic insights in this important area." (PMID 34503236, 2021). "Furthermore, NET-associated IL-1β is involved in the epithelial-to-mesenchymal transition (EMT) process of pancreatic cancer by activating EGFR-ERK pathway." (PMID 34868992, 2021). "In a phase I/II in a series of seven patients with unresectable or metastatic pancreatic cancer, EGFR BATs infusions induced clinical responses with stable disease for 7.4 months, two complete remissions to chemotherapy given after EGFR BATs, and one complete response survivor at 60 months." (PMID 34290709, 2021). "Besides, the pharmacological inhibition of EGFR suppressed the initiation of pancreatic cancer and the activation of HSF1 in vivo." (PMID 33422093, 2021). "Our data indicated that 6-P/EGFR/PI3K/AKT signaling axis might become one of the potential therapies for the treatment of pancreatic cancer." (PMID 34376189, 2021). "Moreover, desmethyl erlotinib is an EGFR inhibitor, and it was approved in 2004 to treat lung and pancreatic cancer." (PMID 32708182, 2020). "The use of a tailored protein fusion between epidermal growth factor (EGF; targeting component) and TAU (effector component) resulted in a cytostatic and apoptotic response in epidermal growth factor receptor (EGFR)-positive pancreatic cancer cells, a finding confirmed in other models." (PMID 33207722, 2020). "Moreover, luteolin has been found to inhibit the migration and invasion of pancreatic cancer cells by trans-inactivating EGFR activity and suppressing the phosphorylation of focal adhesion kinase (FAK) and MMP secretion." (PMID 32224968, 2020). "In humans, nearly 90% of pancreatic cancer patients show mutations in KRAS (cBioportal), and our autochthonous models were based on mutations in KRAS or in upstream signaling receptors (EGFR)." (PMID 31940491, 2020). "In addition to the results found in both cohorts, functional studies were performed in vitro using PANC-1 pancreatic cancer cells either transfected with siRNA against PODXL (siPODXL) or EGFR (siEGFR), or incubated with TGF-β." (PMID 32587323, 2020). "Additionally, X-inactive specific transcript (XIST) promotes the tumor development by triggering miR−133a/EGFR signaling in Pancreatic Cancer." (PMID 32849794, 2020).
pancreatic cancer (continued). "Altogether, our study supports a biphasic model of pancreatic cancer development: an AGO2-independent early phase of PanIN formation reliant on EGFR-RAS signaling, and an AGO2-dependent phase wherein the mutant KRAS-AGO2 interaction is critical for PDAC progression." (PMID 32499547, 2020). "Rap1 activation was required for pancreatic cancer cell migration and EGFR-mediated metastasis." (PMID 32906721, 2020). "Based on these results, Ibr-7 may affect the expression of p-EGFR, leading to DNA damage in pancreatic cancer cells in response to radiation." (PMID 32963499, 2020). "The inhibition of EGFR signaling in pancreatic cancer may lead to a decrease in the growth and invasion of pancreatic tumors." (PMID 32596278, 2020). "However, treatment of SW1990 cells of pancreatic cancer with 1,3,4-O-Bu3ManNAc, which increases the sialylation of one N-glycan site on EGFR, increases the rate of EGFR internalization and degradation." (PMID 33238647, 2020). "Inhibition of EGFR/HER2 enhances radiosensitivity in pancreatic cancer." (PMID 32963499, 2020). "Epidermal growth factor receptor (EGFR) seemed to play an important role as binding leads to an increased activity of carcinogenesis signal transduction pathway and binding of associated ligands (EGF, TGF-alpha) is enhanced in most of pancreatic cancer types." (PMID 32570802, 2020). "In addition, while EGFR enrichment on sEVs from pancreatic carcinoma cell lines is still debated, EGFR was found to be enriched on sEVs derived from mouse xenografts or from the serum of pancreatic carcinoma patients." (PMID 33228060, 2020). "Thus, our in vivo data further confirmed that VPA exhibits anti-tumor activity selectively against EGFR/ErbB2/ErbB3-coexpressing pancreatic cancer likely via induction of miRNAs that target the erbB mRNAs." (PMID 30961642, 2019). "Indeed, the Epidermal Growth Factor Receptor (EGFR) is overexpressed in pancreatic cancer and both antibodies are EGFR inhibitors." (PMID 31694306, 2019). "Targeting ITGα3 might be a promising strategy to inhibit malignant pancreatic cancer by ablating the EGFR signalling pathway." (PMID 30808960, 2019). "EGFR is highly conserved in pancreatic cancer tissues and EGFR inhibition has been shown to be an effective therapeutic strategy against pancreatic cancer, since the EGF/EGFR pathway activates downstream pro-oncogenic signaling pathways, resulting in proliferation and metastasis of cancer cells." (PMID 31572065, 2019). "Thus, VPA treatment simultaneously down-regulates expression of EGFR, ErbB2, and ErbB3 in the ErbB family members-coexpressing pancreatic cancer cells, which in turn results in induction of cell growth inhibition as well as apoptosis." (PMID 30961642, 2019). "Also, in pancreatic cancer cells, EGFR activation correlates with ZO-1 protein localization at the cytoplasm or at the nucleus, and inhibition of EGFR with AG1478 induces the redistribution of ZO-1 to the junctions." (PMID 31783547, 2019). "BRCA2, Smad4, EGFR genes play important role in pancreatic cancer pathway." (PMID 30792708, 2019). "We reported here that VPA-induced simultaneous down-regulation of EGFR, ErbB2, and ErbB3 in pancreatic cancer cells could be mainly attributed to induction of ErbB family members-targeting miRNAs both in vitro and in vivo." (PMID 30961642, 2019). "However, patients with pancreatic cancer benefit little from current existed therapies targeting EGFR, which indicating that it is insufficient to overcome this disease by targeting EGFR alone." (PMID 30961642, 2019). "Given that elevated FAM83A expression results in acquired resistance to EGFR TKIs19, FAM83A expression may help predict the response to EGFR inhibitor therapy in patients with pancreatic cancer." (PMID 31527715, 2019). "To investigate the molecular mechanism by which VPA down-regulated EGFR, ErbB2, and ErbB3 in pancreatic cancer cells, we next explored whether treatment with VPA might modulate EGFR, ErbB2, and ErbB3 mRNA levels." (PMID 30961642, 2019).
pancreatic cancer (continued). "In consideration of this, VPA may be an excellent candidate drug against pancreatic cancer with a strong activity of triple-targeting EGFR, ErbB2, and ErbB3." (PMID 30961642, 2019). "Because ERK lies downstream of KRAS, EGFR cannot induce permanent inhibition in pancreatic cancer, but MEK1/2 inhibitors, which target downstream of KRAS and upstream of ERK, have been approved by the FDA for BRAF mutated melanoma and are being tested in many other cancers." (PMID 30921351, 2019). "Mechanistic investigations revealed that VPA simultaneously down-regulates EGFR, ErbB2 and ErbB3 likely via induction of several critical miRNAs in pancreatic cancer cells, and thereby results in inactivation of downstream Akt and MAPK signaling pathways and induces cell apoptosis and growth arrest." (PMID 30961642, 2019). "In line with our observations, MPT0L145 may provide benefit in sensitizing the clinical use of EGFR inhibitors or gemcitabine for the treatment of pancreatic cancer." (PMID 31514441, 2019). "Apoptosis was induced by adjunctive use of rhein with epidermal growth factor receptor (EGFR) inhibitors in pancreatic cancer cells as verified by cell apoptosis analysis and changes in the expression level of apoptotic/anti-apoptotic proteins BCL-2, BAX, Caspase 3 and Cl-PARP." (PMID 30674340, 2019). "Hence, MEK inhibition rather than inhibition of Raf or PI3K/AKT can result in complete elimination of EGFR-regulated ERK phosphorylation in pancreatic cancer cells." (PMID 31142371, 2019). "Rhein sensitizes human pancreatic cancer cells to EGFR inhibitors through inhibition of STAT3." (PMID 30674340, 2019). "In addition to EGFR and ErbB2, their kin ErbB3 is emerging as an attractive druggable target in pancreatic cancer." (PMID 30961642, 2019). "We therefore evaluated EGFR activation in a pancreatic cancer line, BxPC3." (PMID 29402301, 2018). "One example where hypersialylation can be counterproductive in cancer, our group has shown that sialic acid derived from 1,3,4-O-Bu3ManNAc sensitizes drug-resistant pancreatic cancer cells to tyrosine kinase inhibitors (erlotinib and gefitinib) through attenuation of EGFR signaling." (PMID 29847599, 2018). "Noteworthily, overexpression of EGFR is found up to 90% in pancreatic cancer cells." (PMID 30643798, 2018). "Treatment with the commercially available anti-MUC1 antibody GP1.4 resulted in the inhibition of proliferation and migration of pancreatic cancer cells by activating the internalization of EGFR which leads to sequestration of surface receptors and repression of ERK phosphorylation." (PMID 29987260, 2018). "Notably, hRNase5/ANG, whose level in sera of pancreatic cancer patients, serves as a non-invasive serum biomarker to stratify patients for predicting the sensitivity to EGFR-targeted therapy." (PMID 30449278, 2018). "Overall, EGFR is an emerging candidate for further research in pancreatic cancer therapy." (PMID 30643798, 2018). "In contrast, EGFR TKIs have been approved to treat both lung and pancreatic cancers." (PMID 30449278, 2018). "Additionally, it was recently shown that ROS-induced PKD1-mediated NF-κB activity results in the upregulation of epidermal growth factor receptor (EGFR) signaling components (EGFR and its ligand TGFα) in pancreatic cancer downstream of oncogenic Ras." (PMID 29854077, 2018). "In addition to being heteroallelic (KRASG12D/wt) PANC1 cells exhibit higher EGFR copy number than other pancreatic cancer cell lines (PANC1 > MIA PaCa-2 > Capan-2)." (PMID 29851957, 2018). "Previous studies have demonstrated aberrant expression of both MUC1 and EGFR in pancreatic cancer." (PMID 29987260, 2018). "EGFR and its ligands, epidermal growth factor (EGF) and tumor growth factor-α (TGF-α), are coexpressed in the cells, which may contribute to the aggressiveness of pancreatic cancer by continuous EGFR signaling." (PMID 30400136, 2018).
pancreatic cancer (continued). "MUC1 may interact with other known growth factor receptors including EGF receptor (EGFR) to promote pancreatic cancer." (PMID 29987260, 2018). "Of note, frequency of EGFR overexpression is about 30 to 95% in pancreatic cancer." (PMID 30449278, 2018). "In addition to P19 cells, angiogenin and RNase A also trigger cell proliferation of various pancreatic cancer cells via the EGFR-ERK pathway." (PMID 30534052, 2018). "And this prediction can be validated by the paper published on Oncotarget32, which demonstrated that CHIP is the E3 ligase of EGFR, and it might be a novel tumor suppressor in pancreatic cancer." (PMID 28839186, 2017). "However, due to a high rate of acquired or inherent resistance, EGFR inhibitors are insufficient in effectively treating human pancreatic cancer." (PMID 29262554, 2017). "However, patients with locally advanced pancreas cancer appeared to derive more survival benefit from EGFR-targeted therapy than those with metastatic disease." (PMID 28445400, 2017). "Epidermal growth factor receptor (EGFR) is overexpressed in pancreatic cancer." (PMID 29163770, 2017). "SCH772984 potentiates the cytotoxic effect of CuB on pancreatic cancer cells through complementary inhibition of EGFR, PI3K/Akt/mTOR, STAT3 and ERK signaling, followed by an increase in the pro-apoptotic protein Bim and a decrease in the anti-apoptotic proteins Mcl-1, Bcl-2, Bcl-xl and survivin." (PMID 29262554, 2017). "Similarly, administration of gold NPs loaded with the anti-EGFR antibody cetuximab and gemcitabine was shown to inhibit both pancreatic cancer cell proliferation in vitro and orthotopic pancreatic tumor growth in vivo." (PMID 29144412, 2017). "Epidermal growth factor receptor (EGFR) plays an important role in pancreatic cancer progression." (PMID 29262554, 2017). "EGFR is the example of another gene that is not mutated in pancreatic cancer, but whose expression is very frequently increased in this tumor." (PMID 29156578, 2017). "Epidermal growth factor receptor (EGFR) is overexpressed in up to 60% of human pancreatic cancers, therefore blocking the EGFR pathway could be a promising strategy for treating pancreatic cancers." (PMID 29190951, 2017). "Importantly, we observed downregulation of the pancreatic adenocarcinoma signaling pathway in MYB-silenced pancreatic cancer cells exhibiting suppression of EGFR and NF-κB." (PMID 27354262, 2016). "To evaluate whether HAb18G/CD147 functionally influences EGFR in pancreatic cancer cells, we performed cell growth assays after exposing cells to CyPA and the EGFR inhibitor gefitinib." (PMID 27556697, 2016). "Thus, PA-MSHA inhibited EGFR signaling in pancreatic cancer cells by blocking phosphorylation of several downstream effectors of EGFR." (PMID 27788491, 2016). "Epidermal growth factor receptor (EGFR) has also been shown to play key roles in multiple malignant processes involved in cellular proliferation, apoptosis prevention, drug resistance, cancer stem cell marker expression and metastasis in pancreatic cancer." (PMID 27596051, 2016). "Deregulation expression of miR‐146a affected EGFR signaling in pancreatic cancer model." (PMID 27794184, 2016). "The feedback loop of PIM-1 and the EGFR signalling pathway would be strengthened if the relevance of expression levels between PIM-1 and EGFR could be verified in pancreatic cancer." (PMID 27596051, 2016). "Furthermore, EGFR is known to be upregulated in up to 69-95% of advanced pancreatic cancers and the EGFR tyrosine kinase inhibitor erlotinib combined with gemcitabine demonstrated survival benefit over gemcitabine alone." (PMID 26862857, 2016). "Likewise, inhibition of AGR2 and EGFR expression with RNA interference in pancreatic cancer cell lines reduced cell viability and the transformed phenotype." (PMID 27764193, 2016). "Our previous findings and literature both suggest that HAb18G/CD147 activated EGFR signaling in pancreatic cancer cells may depend on CD44." (PMID 27556697, 2016).
pancreatic cancer (continued). "Another study identified the lumican/EGFR/AKT/HIF1 α signaling pathway as a mechanism to inhibit pancreatic cancer cell survival and proliferation and prolonged survival after tumor resection, which stressed that lumican plays a restrictive role in EGFR-expressing pancreatic cancer progression." (PMID 27399694, 2016). "Previous reports showed that EGFR over-expression may predict shorter survival in multiple solid tumors, including pancreatic tumors." (PMID 27399694, 2016). "PA-MSHA-mediated inhibition of EGFR signaling and activation of the caspase pathway may play an important role in the induction of apoptosis in pancreatic cancer cells." (PMID 27788491, 2016). "Inhibition of EGFR activation resulted in decreased expression of IL-8 in pancreatic cancer cells." (PMID 27362942, 2016). "In this study, we have shown that kaempferol could act as a potent inhibitor of pancreatic cancer cells migratory phenotype, functioning through the blockade of EGFR related Src, AKT, and ERK1/2 signaling pathway." (PMID 27175782, 2016). "Expression of EGFR is common in pancreatic cancer, and has been associated with metastatic potential, but several studies have not found any prognostic effect of EGFR expression on overall survival (OS)." (PMID 27070783, 2016). "We assessed whether PA-MSHA induced apoptosis in pancreatic cancer cells, and evaluated the association between PA-MSHA-mediated anti-tumor effects and EGFR signaling." (PMID 27788491, 2016). "A meta-analysis did however find a survival disadvantage in pancreatic cancer expressing EGFR." (PMID 27070783, 2016). "To further explore the relationship between HAb18G/CD147 and EGFR, we tested whether CyPA, a natural ligand for HAb18G/CD147, could up-regulate EGFR levels in pancreatic cancer cells." (PMID 27556697, 2016). "The prognostic and predictive roles of EGFR expression in pancreatic cancer remain controversial." (PMID 27399694, 2016). "Further studies of EGFR as a potential target for pancreatic cancer treatment are warranted." (PMID 27399694, 2016). "The observation that EGF levels correlated with the degree of lymph node metastasis is consistent with widespread evidence implicating EGF signaling in cancer progression and metastasis, culminating in a phase three trial employing EGFR inhibition in pancreatic cancer." (PMID 26498838, 2015). "Hence, these results imply that pan-EGFR inhibitor inhibits phospho-STAT1 mediated response to regulate MUC4 expression in pancreatic cancer cells, thereby abrogating tumor advancement towards metastasis." (PMID 25686822, 2015). "Finally, the in vivo antitumor efficacy of pan-EGFR inhibitor canertinib was evaluated using pancreatic tumor bearing mice." (PMID 25686822, 2015). "Metastatic human pancreatic cancer cells (the SW1990 line) that are resistant to the EGFR-targeting tyrosine kinase inhibitor drugs (TKI) erlotinib and gefitinib were treated with 1,3,4-O-Bu3ManNAc, a “metabolic glycoengineering” drug candidate that increased sialylation by ∼12-fold." (PMID 25690786, 2015). "Our study provides a strong evidence of profound effects of irreversible pan-EGFR inhibitors (TKIs) in down regulating MUC4 mucin through its effect on the EGFR family proteins resulting in decreased pancreatic cancer cell proliferation, survival and migration." (PMID 25686822, 2015). "Purified crocetinic acid significantly reduced EGFR activity in pancreatic cancer cells." (PMID 26317547, 2015). "EGFR dysregulation is observed in over 87% of patients with pancreatic cancer." (PMID 26429877, 2015). "EGFR expression and surface localization is significantly upregulated in pancreatic cancers." (PMID 26317547, 2015). "Notably, in our study we have demonstrated the role of pan-EGFR inhibitors in limiting the migration of pancreatic cancer cells through FAK mediated pathway." (PMID 25686822, 2015).